PANX1 (pannexin 1)
Diseases named in the same sentence as PANX1 in open-access papers (continued):
Sharing a sentence is not in itself a finding about the gene and the disease.
tumor (continued). "Furthermore, PANX1 inhibition is associated with significant reduction in tumor growth and distant metastasis tested in our ex vivo model of chick chorioallantoic membrane (chick –CAM)." (PMID 33647315, 2021). "Indeed, despite relatively few studies assessing the role of PANX1 in cancer, rodent Panx1 and/or human PANX1 have already been implicated as both a tumor suppressor and tumor facilitator in different types of cancer." (PMID 27099931, 2016). "In addition, Panx1 and Panx2 expression were associated with reduced tumor volume in murine C6 tumor implants, which led to propose them as tumor suppressor genes." (PMID 25018732, 2014). "Additionally, Panx3 may serve as a useful biomarker for certain tumor types, while Panx1 mutations have been linked to metastatic breast cancer." (PMID 40227837, 2025). "Because frequently mutated genes in tumor tissues may have a much greater effect on patients’ survival than SNPs in the same genes, we further investigated the mutation status of PANX1 and APP in liver tumor tissues using the public database of the cBioPortal for Cancer Genomics." (PMID 39090420, 2025). "Finally, due to the association of PANX1 channel function and the pro‐inflammatory and tumor promoter cytokine: interleukin‐1β (IL‐1β), we investigated whether the IL‐1β expression was affected within the TME of BPC Panx1‐deficient mice." (PMID 38327091, 2024). "Furthermore, PANX1 expression and the tumor mutation burden (TMB) were in a positive relation." (PMID 38254708, 2024). "Consequently, a mutation that increases the permeability of PANX1 channels leading to an exacerbated ATP release, also promotes cell motility, but not trans-endothelial migration, suggesting that PANX1 contributes to specific steps during tumor progression." (PMID 34975840, 2021). "Interestingly, PANX1 was associated with significantly better OS in tumors of the basal subtype suggesting differential roles of Panx1 that are dependent on the molecular subtype of the tumor." (PMID 27099931, 2016). "Immunohistochemical analyses further confirmed increased protein expression of representative risk-associated genes, including pannexin 1 (PANX1) and FERM domain containing 8 (FRMD8), in multiple tumor tissues compared with corresponding normal tissues." (PMID 41898689, 2026). "Pannexin 1 (Panx1) is a widely expressed membrane channel that regulates ATP release and purinergic signaling, playing essential roles in inflammation, immunity, and tumor progression." (PMID 40978734, 2025). "In human cSCC patient‐derived tumours and aged epidermis, immunofluorescence microscopy analysis using a small cohort of samples indicated that both PANX1 and PANX3 were visibly reduced in cSCC tumours." (PMID 39560179, 2025). "This review aims to consolidate the most relevant and up-to-date information on Panx1, exploring its structure, regulation, and functions in innate and adaptive immunity, inflammation, and the tumor microenvironment." (PMID 40978734, 2025). "Overall, multiple cell types in cSCC tumours and adjacent skin are positive for PANX1 protein expression." (PMID 39560179, 2025). "In the context of tumor progression, Panx1 plays key roles in multiple aspects, including cell migration, metabolism, and the immune response within the tumor microenvironment." (PMID 40978734, 2025). "Panx1 exerts complex, context-dependent roles in cancer, acting as both a promoter and suppressor of tumor progression depending on the tumor type and microenvironment." (PMID 40978734, 2025). "We also demonstrated that PANX1 promotes cancer cell properties such as growth and migration through its channel activity and is present in all regions within the cSCC tumour microenvironment and adjacent skin." (PMID 39560179, 2025). "Panx1 drives tumor progression through ubiquitous overexpression that accelerates malignant proliferation and invasion, whereas Panx3 exerts tumor-suppressive effects." (PMID 40909173, 2025).
tumor (continued). "Pannexin 1 plays key roles in multiple aspects of tumor development, including cell migration, metabolism, and immune response within the tumor microenvironment." (PMID 40978734, 2025). "In our patient sample cohort, we found that PANX1 protein is upregulated whereas PANX3 mRNA is downregulated in human cSCC tumour fragments compared to patient‐matched normal skin." (PMID 39560179, 2025). "In cutaneous squamous cell carcinoma (cSCC), Panx1 and Panx3 exhibit divergent tumor-modulatory roles." (PMID 40909173, 2025). "According to pathologist observations PANX1 is present throughout all regions of cSCC tumours and adjacent skin, with relative staining intensity slightly increased in the tumour." (PMID 39560179, 2025). "In contrast to the tumor-promoting roles discussed earlier, some studies have suggested a potential tumor-suppressive function of Panx1 in specific contexts." (PMID 40978734, 2025). "Our cohort of patient‐matched samples revealed most sample pairs exhibited the pattern of higher PANX1 in cSCC tumours, but interpatient variability was noticeable for PANX1 levels in both skin and cSCC samples." (PMID 39560179, 2025). "Within the tumour PANX1 localizes to all regions, including tumour nests which house cSCC cancer cells and tumour stroma which contains tumour‐infiltrating lymphocytes, cancer‐associated fibroblasts and blood vessels." (PMID 39560179, 2025). "Mechanically, through Bulk-RNA sequencing and experiments, we found that PANX1 promoted tumor progression and immune regulation via the ATP release to active NOD1/NFκB signaling pathway in PDAC." (PMID 39882247, 2024). "Overall, we observed that BPC‐Panx1−/− mice had similar tumor incidence, survival, and mouse weight among sexes compared to Panx1‐wildtype counterparts." (PMID 38327091, 2024). "We found that high PANX1 expression in tumor cells was positively correlated with a high density of tumor-infiltrating CD11+ DCs and CD8+ T cells in patients." (PMID 38195677, 2024). "Mice subcutaneous transplantation model were established to evaluate the effect of PANX1 on tumor growth." (PMID 39882247, 2024). "In vivo results showed that the knockdown of PANX1 in tumor cells reduced their response to oxaliplatin, thereby reducing anti-tumor immunity and tumor-infiltrating cells." (PMID 39456655, 2024). "If the tumor is intrinsically TNFα-sensitive, TNFα will initiate apoptosis and promote PANX1 cleavage." (PMID 38195677, 2024). "The results clearly demonstrated that Purinergic genes P2RX7 and PANX1 protein expression levels were significantly higher in tumor tissues than in normal kidney tissues." (PMID 38180750, 2024). "Consistent with our results, overexpression of PANX1 was associated with poor prognosis of PDAC and increased infiltration of immunocytes, such as tumor associated fibroblasts, macrophages and neutrophils." (PMID 39882247, 2024). "We found that knockdown of PANX1 alone slightly decreased the number of tumor-infiltrating CD8+CD3+CD45+ T cells and effector/memory CD8+ T cells, and CD11c+MHC-IIHiCD11b+F4/80-CD3-CD45+ dendritic cells." (PMID 38195677, 2024). "We obtained the protein expression data of Purinergic genes GNAI2, GNAI3, GNAO1, P2RX4, P2RX7, and PANX1 in normal tissues and tumor tissues in the UALCAN database." (PMID 38180750, 2024). "The analysis results showed that the expression levels of Purinergic genes GNAI2, GNAI3, P2RX4, P2RX7, and PANX1 were significantly higher in tumor tissues than in normal tissues, consistent with the mRNA expression results." (PMID 38180750, 2024). "When Panx-1 was compared between the tumor and control groups, differences were observed between G2 and the control (p = 0.026; Z = −2.221) and G3 and the control (p < 0.001; Z = −3.997)." (PMID 36833374, 2023). "In agreement, Panx1 gene expression was positively correlated with the expression of IL-6 in LUAD tumor tissues." (PMID 37385076, 2023).
tumor (continued). "The proposed antitumorigenic mechanisms of Panx1 reduce cell proliferation, cell motility, anchorage-independent growth, and tumor growth in experimental animals." (PMID 36833374, 2023). "In contrast, expression of genes correlated with worse survival and hypoxia (PANX1, NT5E, ADORA2B, and P2RY2) was associated with tumor cells and the squamous PDAC subtype, correlating with hypoxia, inflammation, and worse prognosis." (PMID 36942939, 2023). "Taken together, these findings strongly suggest that P2X7R associated with pannexin-1 and the consequent downstream NLRP3 activation are implicated in the pathogenesis of AOM/DSS-mediated inflammation and tumor development." (PMID 35563010, 2022). "We then investigated the role of PANX1 in quercetin-induced RMS tumor suppression by genetically targeting PANX1 using siRNA." (PMID 35194046, 2022). "Although the relationship between PANX1 and exATP/exADO has been reported, the immunomodulatory role of PANX1 in the tumor microenvironment still requires further investigation." (PMID 35884429, 2022). "Knockdown of AHNAK in PANX1-expressing Rh18 and Rh30 cells abrogated the PANX1-mediated reduction in cell viability, migration, and increase in anoikis, suggesting that PANX1 regulation of RMS tumor malignant properties involves its interaction with AHNAK." (PMID 33564071, 2021). "The correlation between PANX1 and tumor-infiltrating immune cells was investigated using the TIMER 2.0." (PMID 34796785, 2021). "In particular, the complex and contrasting roles of Panx1/P2X7R signalosome in tumor facilitation and/or inhibition is discussed in regard to the early/late phases of the carcinogenesis." (PMID 33806300, 2021). "Accumulating evidence also indicates that PANX1 is overexpressed in a variety of cancers and regulates the tumor immune microenvironment via ATP release channels." (PMID 34796785, 2021). "Increasing PANX1 levels abrogated the proliferative and migratory potential of eRMS and aRMS cells, inhibited 3D tumor spheroid growth and induced regression of established spheroids through the induction of apoptosis." (PMID 33564071, 2021). "Our data suggest that PANX1 interacts with AHNAK in specialized plasma membrane compartments resembling pseudopodia, which are known to be associated with tumor cell migration and invasion." (PMID 33564071, 2021). "TIMER2.0 was used to determine the relationship between PANX1 expression and various infiltrating immune cells in diverse cancer types, to better understand the role in tumor immune infiltration." (PMID 34796785, 2021). "Altogether, these results indicate that the PANX1 tumor inhibitory function in RMS involves its interaction with AHNAK." (PMID 33564071, 2021). "Pannexin 1 (PANX1) channel is a critical ATP-releasing pathway that modulates tumor immunity, progression, and prognosis." (PMID 34796785, 2021). "Currently, only a modest amount of research has been conducted on the involvement of PANX1 in tumor progression and immune response." (PMID 34796785, 2021). "The upregulated GJA1 gene was further investigated as ectopic expression of its protein product connexin 43 (Cx43) in RMS cells was previously shown to elicit a tumor-suppressive phenotype similar to that of PANX1." (PMID 33564071, 2021). "The expression of Panx1 was positively correlated with tumor TNM staging and venous invasion, negatively correlated with overall survival." (PMID 31737105, 2019). "The number of lung metastasis tumor nodules in Panx1 knockout mice was significantly reduced than that in WT mice." (PMID 31737105, 2019). "For instance, PANX1 was reported to play tumor suppressor roles in C6 glioma cells, in squamous and basal cell carcinomas of the skin, and in rhabdomyosarcoma." (PMID 31817827, 2019). "Panx1 expression levels was positively correlated with microvascular involvement (P=0.008) and tumor lymph node metastasis stages (P=0.020) in patients with HCC." (PMID 31737105, 2019).
tumor (continued). "Immunoblot analysis revealed that all tumor samples were positive for PANX1 expression, with the characteristic banding pattern." (PMID 30654593, 2019). "In this study, elevated expression of Panx1 in HCC was positively associated with vascular invasion, tumor metastasis and poor prognosis of patients." (PMID 31737105, 2019). "Altogether the data presented here constitute the first evidence of PANX1 tumor suppressive functions in human cancer and suggest that increasing PANX1 levels would be a novel therapeutic approach for RMS." (PMID 30459312, 2018). "In those cells, Panx1 expression had a wide range of anti-tumour activity by reducing in vitro cell proliferation, cell motility, anchorage-independent growth and tumour growth in nude mice." (PMID 29865195, 2018). "Collectively, these complementary approaches suggest that PANX1 tumor suppressive function in RMS involves a mechanism independent of its canonical channel activity." (PMID 30459312, 2018). "Conversely, our data suggest that PANX1 lacks its cell surface channel function in eRMS and aRMS cells and that its tumor suppressive effects are mediated through a channel-independent mechanism." (PMID 30459312, 2018). "The numerous tumor-suppressive effects of PANX1 in RMS cells in vitro prompted us to explore its impact on tumor growth in vivo." (PMID 30459312, 2018). "Panx1 channel assists in accumulating immune-stimulatory ATP versus immunosuppressive adenosine within the tumour microenvironment." (PMID 29865195, 2018). "Similar to wild-type PANX1, expression of the C265S mutant lead to ~50% reduction in tumor volume at endpoint." (PMID 30459312, 2018). "Taken together, these data suggest that the PANX1-mediated tumor suppressive effects in RMS are independent from its canonical channel activity." (PMID 30459312, 2018). "Conversely, tumors formed by PANX1-expressing eRMS and aRMS cells grew significantly slower, which was clearly depicted by a reduction of ~50% in their tumor weight at the endpoint." (PMID 30459312, 2018). "Here, we show that PANX1 is down-regulated in human eRMS and aRMS primary tumor specimens and patient-derived cell lines, when compared to normal differentiated skeletal muscle cells and tissue." (PMID 30459312, 2018). "On the pannexin side, the majority of reports point towards a tumour promoting effect of Panx1 expression." (PMID 27229305, 2016). "As was mentioned before, even though the majority of reports in the literature to date point towards an over-expression or amplification of Panx1 in cancer cells and tumours, there are also important exceptions to this trend." (PMID 27229305, 2016). "These nucleotides can also be released by other Panx1-independent mechanisms, and are very important as paracrine signals to effector leukocytes that mediate the immune response against the dying tumor cells." (PMID 27229305, 2016). "Knocking down Panx1 from the most aggressive of the melanoma lines suppresses certain oncogenic characteristics, and knock-down also diminishes tumor size and metastases when the cells are implanted onto the chorioallantoic membrane of a chicken embryo." (PMID 24600404, 2014). "The release of ATP through activated Panx1 hemichannels was also shown to accelerate the assembly of multicellular C6 tumor cells aggregates in a 3D culture system." (PMID 25018732, 2014). "Furthermore, in the context of chemotherapy-induced tumor immunogenicity, Panx1 facilitates ATP release through a caspase-3-dependent mechanism activated by TNF-α." (PMID 40978734, 2025). "Additionally, Panx1 plays a dual role in tumor progression, acting either as a promoter or a suppressor depending on the cellular and microenvironmental context." (PMID 40978734, 2025). "Here, extracellular ATP provides energy status information in the tumour microenvironment by way of purinergic signalling through ATP-sensitive purinergic receptors and ATP release mechanisms, including the large pore channel pannexin 1 (PANX1)." (PMID 41250870, 2025).
tumor (continued). "Panx1 expression was positively correlated with higher extracellular ATP and adenosine levels in the TME, which induced an immunosuppression mechanism also supported by high expression of CD39/CD73, due to the tumor-associated neutrophil increase." (PMID 40227837, 2025). "Pannexins, particularly Panx1, also have a significant impact on tumor progression." (PMID 40227837, 2025). "Pannexin 1 (Panx1) has emerged as a key regulator in a wide array of physiological and pathological processes, including inflammation, cell death, immune activation, and tumor progression." (PMID 40978734, 2025). "Future studies could investigate the potential role of PANX1 in immune infiltration/evasion and angiogenesis in cSCC tumours." (PMID 39560179, 2025). "However, there was a higher abundance of Panx1 in tumor cells and stroma from patients with tumor–node–metastases (TNM) III compared to patients with TNM I and II." (PMID 40227837, 2025). "Thus, to localize PANX1 expression within the various cells of the cSCC tumour microenvironment, we performed immunohistochemistry of tumours and adjacent skin tissue from the most common anatomical subtypes of the scalp, ear and cheek." (PMID 39560179, 2025). "In addition, recent report shows that Panx1 overexpression can facilitates tumor growth in Panc02, a mice PDAC cell line." (PMID 40909173, 2025). "Panxs may be involved in the process of tumour development: truncating mutations of Panx1 promote the metastasis of colon-rectal carcinoma (CRC), allowing tumour cells to survive mechanical stress in the microcirculation by releasing ATP." (PMID 40646589, 2025). "In this study which contained a much larger N value of 502 HNSCC tumours and 44 adjacent normal tissues, PANX1 mRNA was found to be significantly increased in a subset of HNSCC (P = 6.54 × 10−14), with a FC of +2.20 compared to controls, similar to what was seen in cSCC." (PMID 39560179, 2025). "Within the tumour PANX1 staining was present in both tumour nests and stromal regions but seemed to be more prominent within the cSCC cancer cells as opposed to the tumour‐infiltrating lymphocytes and stromal fibroblasts present in the stroma surrounding tumour nests." (PMID 39560179, 2025). "PANX1 was shown to be overexpressed in tumor samples in the further investigation." (PMID 38254708, 2024). "Moreover, inhibition of the PANX1-ATP-P2RX7 axis by a small molecule inhibitor significantly increased tumor volume after chemotherapy treatment and reduced dendritic cell maturation and T-cell infiltration." (PMID 38195677, 2024). "Future preclinical studies should include the combination strategies in which PANX1 inhibition could be considered as means to stimulate cytotoxic T‐cell tumor infiltration to improve the efficacy of immunotherapies." (PMID 38327091, 2024). "In particular, PANX1 plays a key role in immune regulation and tumor progression in PDAC." (PMID 39882247, 2024). "However, knockdown of PANX1 significantly decreased tumor-infiltrating CD8+T and DCs in response to chemotherapy." (PMID 38195677, 2024). "We propose that PANX1‐targeted therapy could be explored as a strategy to increase tumor‐infiltrating lymphocytes to boost anti‐tumor immunity." (PMID 38327091, 2024). "Additionally, Panx1 involves tumor migration and metastasis, as mechanical forces on tumor cells induce the opening of Panx1 hemichannels on vascular endothelium, leading to ATP release that promotes metastasis." (PMID 37711629, 2023).